EPO (erythropoietin)
Diseases named in the same sentence as EPO in open-access papers (continued):
Sharing a sentence is not in itself a finding about the gene and the disease.
asthma (13 papers, 2020 to 2025). "Our findings demonstrate that EPO-BM-MSCs rescue epithelial cell injury by mitochondrial donation by upregulating HO-1 to alleviate asthma inflammation, providing novel evidence for the therapeutic potential of EPO-BM-MSCs in asthma." (PMID 41023810, 2025). "These limitations highlight that while our findings establish a mechanistic basis for EPO-BM-MSCs in asthma, comprehensive long-term studies are essential to validate their therapeutic potential and address regulatory requirements for clinical use." (PMID 41023810, 2025). "In this study, we used in vivo and in vitro asthma models to elucidate the effect of EPO-BM-MSCs on epithelial mitochondrial dysfunction." (PMID 41023810, 2025). "Collectively, we have demonstrated the therapeutic efficacy of EPO-BM-MSCs, with the ability to rescue epithelial cell injury by mitochondrial donation by upregulating HO-1, M-sec, and Miro1, in asthma inflammation." (PMID 41023810, 2025). "While the current study provides valuable insights into the potential of EPO-BM-MSC therapy for asthma, it is constrained by its sample size, type, and duration." (PMID 41023810, 2025). "While our study demonstrates the short-term therapeutic effects of EPO-BM-MSCs in asthma models, the long-term impacts of this treatment remain unaddressed and warrant further investigation." (PMID 41023810, 2025). "Recent advancements in the field of BM-MSCs therapy for asthma along with our current study have demonstrated promising results, positioning BM-MSCs and EPO-BM-MSCs as potential therapeutic options for asthma." (PMID 41023810, 2025). "The reduction in mucin expression complements the observed decrease in Th2 cytokines and airway inflammation, highlighting the multi-faceted therapeutic potential of EPO-BM-MSCs in asthma." (PMID 41023810, 2025). "EPO plays an important role in the pathogenesis of asthma by mediating oxidative events, leading to the production of ROS and RNS." (PMID 35296330, 2022). "Our results further demonstrate that EPO-BM-MSCs suppress the expression of mucin markers (MUC5AC and MUC5B) in asthmatic lungs, which is critical for alleviating airway obstruction—a hallmark of severe asthma." (PMID 41023810, 2025). "Thus, HO-1 upregulation contributes to enhanced anti-inflammatory efficacy of EPO-BM-MSCs in OVA-induced asthma mice." (PMID 41023810, 2025). "Therefore, we conclude that EPO-BM-MSCs have strong ability to relieve OVA-induced airway inflammation in asthma mice." (PMID 41023810, 2025). "The fact of mitochondrial transport from EPO-BM-MSCs to mtCC1-2 cells in vitro led us to further examine if engrafted EPO-BM-MSCs can donate mitochondria to bronchial epithelial cells in OVA-induced asthma mice." (PMID 41023810, 2025). "Studies on EOXs role in the pathology of asthma have revealed that the composition of EOXs in patients with asthma and healthy individuals are similar in size and carries important enzymes such as EPO (Eosinophil peroxidase), MBP (Major basic protein), and ECP (Eosinophil cationic protein)." (PMID 35550636, 2022). "Improvements in cytoprotection and preservation of lung structure were described for the combined application of MSC plus erythropoietin in BPD and the application of erythropoietin gene-modified MSC in asthma where all disease-driving pathologies were more efficiently inhibited by MSC modification." (PMID 32138309, 2020). "Furthermore, studies are needed to elucidate the exact mechanisms of action of EPO-BM-MSCs in asthma, which could pave the way for the development of more targeted and effective therapies." (PMID 41023810, 2025). "Our previous study has established that EPO-BM-MSCs are capable of attenuating asthmatic airway inflammation and remodeling in OVA-challenged asthma mice." (PMID 41023810, 2025). "Intratracheal transplantation of EPO-BM-MSCs alleviated airway inflammation, asthmatic phenotype, and mitochondrial dysfunction in the lungs of OVA-induced asthma mice." (PMID 41023810, 2025).
asthma (continued). "To further dissect the activity of EPO-BM-MSCs in affecting OVA-induced asthmatic phenotype, we established an OVA-induced mouse model of asthma and performed EPO-BM-MSCs or BM-MSCs local transplantation via intratracheal administration." (PMID 41023810, 2025). "Taken together, these findings indicate that EPO-BM-MSCs can ameliorate epithelial mitochondrial function and suppress apoptosis in the lungs of OVA-induced asthma mice." (PMID 41023810, 2025). "Furthermore, Western blot analysis of lung tissues revealed that EPO-BM-MSCs markedly suppressed the expression of mucin markers MUC5AC and MUC5B in OVA-induced asthma mice." (PMID 41023810, 2025). "A considerable reduction of EPO was observed in OVA-LPS sensitized mice after oral treatment with probiotics (0.21 ± 0.02) compared to the non-treated asthma group (0.34 ± 0.04)." (PMID 35296330, 2022).
lung carcinoma (13 papers, 2013 to 2025). "Furthermore, the literature describes only one reported case of an EPO-producing tumor caused by lung cancer." (PMID 40502212, 2025). "Furthermore, age is also identified as an important risk factor for CRA among lung cancer patients, with elderly patients being more susceptible due to decreased hematopoietic raw material absorption, erythropoietin (EPO) secretion, and bone marrow erythropoiesis." (PMID 38562035, 2024). "In a xenograft model mimicking EPO treatment in lung cancer patients, knockdown of EPOR impaired tumor growth, cellular respiration, mitochondrial content, and iNOS expression and AKT phosphorylation of lung cancer xenografts." (PMID 37746281, 2023). "Based on these differences, targeted inhibitor treatments are predicted to reduce EPO-induced survival signaling in the lung cancer cells with only marginally affecting EPO-induced signaling in healthy erythroid progenitor cells." (PMID 27494133, 2016). "The model suggested that JAK2 inhibition in combination with EPO treatment affects lung cancer cells to a much higher extent than erythroid progenitor cells." (PMID 27494133, 2016). "Since we aimed to diminish the EPO-induced STAT5-mediated survival signal in the lung cancer cells, we focused on potential targets for more effective inhibition in H838 cells." (PMID 27494133, 2016). "EPO expression score was significantly elevated in lung cancer and lymphoma (compared to benign tissues), while EPOR expression score was significantly elevated in lymphoma, thyroid, uterine, lung and prostate cancers (compared to benign tissues)." (PMID 24004818, 2013). "The EPO expression score was significantly elevated in lung cancer (p = 0.003) and lymphoma (p = 0.018)." (PMID 24004818, 2013). "Having demonstrated that EPO potentially targets not only CFU-E cells but also lung cancer cells, it remained to be addressed if the signaling upon EPO stimulation is identical between the different cell types or if there is a therapeutic window to specifically target lung cancer cells." (PMID 27494133, 2016). "Analogous conclusions could also be obtained in lung cancer, prostate cancer and ovarian cancer, which indicated EPO/EPOR signaling system was tightly connected with tumor cell apoptosis, hypoxia resistance and metastasis." (PMID 23825635, 2013). "In conclusion, we believe that more high-quality, large sample, multicenter, fully randomized, double-blind controlled clinical trials are needed to demonstrate whether erythropoietin has an effect on the survival of lung cancer patients, so as to obtain more valuable meta-analysis results." (PMID 38967734, 2024). "In our IHC tissue arrays in which tissue hypoxic status was unknown, EPO expression score was significantly elevated in lung cancer (p = 0.003) and lymphoma (p = 0.018), but not in RCC (p = 0.91)." (PMID 24004818, 2013).
atherosclerosis (12 papers, 2012 to 2024). A disease characterized by the build-up of fatty material and calcium deposition in the arterial wall resulting in partial or complete occlusion of the arterial lumen. "Selective induction of erythrocytosis with low-dose erythropoietin further exacerbated atherosclerosis with prominent ferroptosis, lipid peroxidation, and endothelial damage." (PMID 35587375, 2022). "EPO has shown its effect beyond hematopoiesis, such as suppression of atherosclerosis and prevention of cardiac apoptosis." (PMID 32373157, 2020). "Our findings provide advanced information in EPO-conferred protection and suggest that βCR may have therapeutic value in treating atherosclerosis-related cardiovascular diseases." (PMID 26101463, 2015). "Studies evaluating the effect of rEPO or an EPO derivative ARA290 have shown that rEPO inhibits macrophage activation while promoting phagocytic activity through activation of the EPOR/βcR heterodimer in experimental models of atherosclerosis and autoimmune neuritis." (PMID 32184703, 2020). "Further studies are necessary to investigate whether other immune cells involved in the inflammatory response and in atherosclerosis may be more sensitive to this recommended dose of EPO and whether higher doses of EPO as used in cardiovascular trials do affect monocyte gene expression." (PMID 22957013, 2012). "The inflammatory mediators, postulated as a major mechanism of RDW and atherosclerosis, including C-reactive protein, brain natriuretic peptide, erythropoietin, nitric oxide, fibrinogen, and cytokines, were not measured." (PMID 31324033, 2019). "Nevertheless, whether carbamylated EPO and ARA290 afford the comparable protection as EPO, from the formation of foam cells and atherosclerosis, remains in need for further investigations." (PMID 26101463, 2015). "Accordingly, these findings suggest that βCR plays a key role in the nonhematopoietic benefits of EPO and may have therapeutic value in the treatment of atherosclerosis and disorders of lipid metabolism." (PMID 26101463, 2015). "Consistent with the more severe atherosclerosis phenotypes, there was more prominent staining for lesional RBCs, iron, TUNEL, 4-HNE, and macrophage TfR in VFEpoR mice injected with EPO compared with VFEpoR mice not injected with EPO." (PMID 35587375, 2022).
bipolar disorder (12 papers, 2010 to 2025). A disorder of the brain that causes unusual shifts in mood, energy, activity levels and the ability to carry out day-to-day tasks. "In another double-blind, randomized, placebo-controlled, phase II trial on bipolar disorder, EPO was shown to improve processing speed for learning, attention (p < 0.05), executive functions (p < 0.05), recognition of happy faces (p < 0.05), and sustained attention (p < 0.05)." (PMID 29670547, 2018).
coronary artery disease (12 papers, 2006 to 2023). "The aim of this study was to analyse the association between the serum erythropoietin level and coronary collateral development in patients with coronary artery disease and chronic total occlusion." (PMID 27561278, 2016). "In this study, we aimed to explore the association between the serum EPO level and coronary collateral development in patients who had coronary artery disease with chronic total occlusion (CTO), patients who had CAD without CTO and in patients who did not have CAD." (PMID 27561278, 2016). "For instance, hemoglobin level was significantly increased by administration of empagliflozin, accompanied by increased erythropoietin levels and reduced serum ferritin in type 2 DM patients with coronary artery disease in the EMPA-HEART CardioLink-6 randomized clinical trial." (PMID 36114995, 2023). "EPO levels in patients with vs. without coronary artery disease were 15.00 (9.95–29.55) vs. 13.55 (9.58–22.60) (p = 0.272) and 15.40 (8.95–24.55) vs. 11.65 (8.00–17.60) (p = 0.092), respectively." (PMID 33330669, 2020).
left ventricular hypertrophy (12 papers, 2011 to 2025). Enlargement of the LEFT VENTRICLE of the heart. "Specifically, it is suggested that exogenous erythropoietin generated by ESAs can largely increase C-terminal fibroblast growth factor 23 (FGF23) levels, which is significantly associated with left ventricular hypertrophy and an increased risk of mortality." (PMID 36170343, 2022). "Although the underline mechanism has not been elucidated, it is suggested that exogenous erythropoietin generated by ESAs can largely increase C-terminal fibroblast growth factor 23 (FGF23) level, which is significantly associated with left ventricular hypertrophy and an increased risk of mortality." (PMID 35445052, 2022). "FGF23 has been described to have effects on the heart, promoting left ventricular hypertrophy (LVH); the liver, leading to production of inflammatory cytokines; the bones, inhibiting mineralization; and the bone marrow, by reducing the production of erythropoietin (EPO)." (PMID 30909513, 2019).
cervical carcinoma (11 papers, 2006 to 2024). A carcinoma arising from either the exocervical squamous epithelium or the endocervical glandular epithelium. "These include the up-regulation of TNFRSF18 (also known as glucocorticoid-induced TNFR-related gene) and the survival factor erythropoietin which has been shown to be involved in survival of human breast and cervix carcinoma cells." (PMID 18691394, 2008). "Interestingly, EPO or stem cell factor (SCF) alone produced a modest number of cervical cancer cell colonies, whereas the combination EPO/SCF induced a significantly more." (PMID 25426117, 2014). "Similarly, co-stimulation with EPO/SCF induced a significantly higher number of migrating cervical cancer cells than either cytokine alone." (PMID 25426117, 2014). "Co-signaling of EPO and the stem cell factor (SCF) activated both ERK1/2 and JAK2/STAT5, and had a cooperative effect on the migration ability of cervical cancer cells." (PMID 34299300, 2021). "On the contrary, EPO in a JAK-dependent manner enhanced cell migration and activated RhoA protein via MAPKs an in EPOR-expressed cervical cancer cell line." (PMID 34299300, 2021). "Whereas SCF and EPO/SCF induced strong, sustained phosphorylation of ERK1/2, EPO solely induced only a modest, transient activation of ERK1/2 in cervical cancer cells." (PMID 34299300, 2021). "It has been shown that EPO and SCF may have a synergistic effect on erythropoiesis and migration of cervical cancer cells, and EPOR and KIT may even form a receptor complex." (PMID 35887076, 2022). "A retrospective, case control study of 147 with carcinoma of the cervix or vagina treated with chemoradiotherapy with or without erythropoietin showed a 23 versus 3% incidence of TE." (PMID 16722547, 2006).
Cirrhosis (11 papers, 2013 to 2025). A chronic disorder of the liver in which liver tissue becomes scarred and is partially replaced by regenerative nodules and fibrotic tissue resulting in loss of liver function. "Our group has previously shown that G-CSF in combination with erythropoietin can decrease the risk of septic shock in patients with decompensated cirrhosis." (PMID 34820395, 2021). "On the other hand, information regarding patients with cirrhosis is limited, and there is debate about the plasma erythropoietin (EPO) levels in these individuals." (PMID 38610814, 2024). "In contrast, inadequate EPO response in advanced cirrhosis might be attributed to poor hepatic synthesis capacity, decreasing co-factor levels, and inflammatory feedback mechanisms." (PMID 38610814, 2024). "Ultimately, the source of a potential increase in EPO production during certain stages of cirrhosis—whether from the kidney or liver—remains a lingering question." (PMID 38610814, 2024). "EPO has been shown to directly modulate Kupffer cell activity, the liver-resident macrophage population, and preliminary clinical data suggested that EPO, in combination with granulocyte colony-stimulating factor, may improve outcomes in patients with decompensated cirrhosis." (PMID 40697664, 2025). "These animal and human studies indicate that the administration of EPO or the co-administration of EPO and G-CSF is a promising therapeutic strategy for patients with decompensated cirrhosis who cannot survive without a liver transplant." (PMID 26404356, 2015).
epilepsy (11 papers, 2008 to 2024). A brain disorder characterized by episodes of abnormally increased neuronal discharge resulting in transient episodes of sensory or motor neurological dysfunction, or psychic dysfunction. "Report of a Case: A 17-year-old girl with epilepsy had progressively elevated hemoglobin levels and low erythropoietin levels." (PMID 39767963, 2024). "The authors experimented with the pentylenetetrazol (PTZ)-induced kindling animal model and affirmed that CUR significantly protected against epilepsy via upregulation of klotho and erythropoietin (EPO), as well as via the reduction of neuronal cell death." (PMID 36678859, 2023). "Regarding epilepsy, there were 3 eligible studies included (EPO group/control group = 310/303), and significant heterogeneity was detected among these trials (χ2 = 4.46, P = 0.11; I2 = 55.2%)." (PMID 36699298, 2022). "In rats with experimental epilepsy, EPO protected myocardial cells from apoptosis via the JAK2/STAT5 pathway, and the inhibition of JAK2/STAT5 signalization by AG490 reduced the antiapoptotic effects of EPO." (PMID 34281163, 2021). "Future studies, using the appropriate animal model and the optimum treatment parameters, are necessary to support the erythropoietin-derived peptide mimetic design as a reliable therapeutic strategy to prevent the onset and progression of epilepsy." (PMID 33202963, 2020). "The PI3K/Akt and ERK1/2 signaling pathways mediate the EPO-modulated calcium influx in KA-induced epilepsy." (PMID 27926529, 2017). "Given the previous findings regarding the neuroprotective, anti-inflammatory and antiepileptogenic effects of erythropoietin, it is reasonable to suggest that the development of erythropoietin-derived mimetic peptides could be a therapeutic target to treat epilepsy and drug-resistant epilepsy." (PMID 33202963, 2020).